RALA (RAS like proto-oncogene A)
Diseases named in the same sentence as RALA in open-access papers (continued):
Sharing a sentence is not in itself a finding about the gene and the disease.
tumor (continued). "In addition, we detected the expression level of RALA in 6 pairs of fresh OS tissues and normal tissues and found that RALA protein and mRNA expression levels in the tumor specimens were higher than those in the paired normal specimens." (PMID 36817861, 2023). "The maximum single tumor in RALA overexpression group was 2.05 cm3 in size and 0.8 g in weight." (PMID 36817861, 2023). "In addition, we observed an interesting phenomenon that the differential expression of RALA not only featured in tumor and normal tissues but was present in immune cells." (PMID 36817861, 2023). "RALA, a kind of small Ras-like guanosine triphosphatases, has been identified as a potential therapeutic target in several types of tumor, but its role in OS remains largely unknown." (PMID 36817861, 2023). "Previous studies have focused on the role of RALA variants in tumor cell proliferation and metastasis, but RALA has never been reported to be associated with FCD." (PMID 35846790, 2022). "RALA protein as a tumor antigen can induce the production of serum RALA antibody (s-RALA-Abs)." (PMID 36466919, 2022). "However, further clinical and general biological studies are needed to verify the function of RALA in tumor cells." (PMID 36466919, 2022). "For pan-cancer, the level of its expression might be closely related to tumor staging, and the specific function of RALA in each cancer needs to be further studied." (PMID 36466919, 2022). "We also analyzed the interaction between RALA and tumor immunity." (PMID 36466919, 2022). "Constitutively activated RalA has been shown to be required for anchorage-independent growth of cancer cells, while RalB plays a role in invasion, metastasis and the avoidance of apoptosis in tumor cells." (PMID 33214225, 2021). "Our experiments suggest that RalA/B contribute to exosome secretion in several tumor cell lines, of different origins, implying that they might function pleiotropically over various cancers." (PMID 33404012, 2021). "Therefore, while depletion of RalA favors in vivo tumor growth by enhancing 4T1 proliferation potential, it is likely that additional non-cell autonomous factors are responsible for the decreased tumor growth observed upon RalB depletion." (PMID 33404012, 2021). "RalA and RalB control lung tropism of pro-metastatic tumor extracellular vesicles (EVs)." (PMID 33404012, 2021). "However, it is important to keep in mind that all these proteins regulating EV trafficking, including RalA/B, contribute to tumor progression through both exosome dependent and exosome independent functions." (PMID 33404012, 2021). "Interestingly, PNT2-C2 the normal epithelial control cell, internalised less RALA-AuNP complexes, implying preferential tumour specific activity." (PMID 34538237, 2021). "We thus built on this relevant tumor model and decided to test the hypothesis that RalA and RalB could orchestrate pro-metastatic functions by tuning the molecular mechanisms driving the secretion levels and nature of EVs." (PMID 33404012, 2021). "Importantly, RalA/B are crucial for the organ targeting of tumor EVs, and, as a consequence, for the seeding of pre-metastatic niches." (PMID 33404012, 2021). "However, little emphasis has been made on comparison of individual roles of RalA and RalB and their downstream partners in tumor progression." (PMID 21714887, 2011). "Since we do not see the effect of S194A mutation on RALA activation in MCF7 and MiaPaC2 cells but see a significant inhibition of tumor growth, we can speculate the role this phosphorylation could have in tumor formation may stem from its effect on RALA localization." (PMID 40568758, 2025). "Hence, it was for the first time revealed that targeting the RALA in tumor endothelial cells maybe a potential therapeutic target for LUAD." (PMID 36483553, 2022). "RALA is a tumor antigen, so s-RALA-Abs could be used as potential biomarkers." (PMID 36466919, 2022).
tumor (continued). "Therefore, it is hypothesised that RALA-AuNP complexes should result an increased AuNP internalisation efficiency, leading to significant radiation dose enhancement in PCa tumour models." (PMID 34538237, 2021). "In conclusion, our work revealed that overexpression of miR-181a causes cell growth inhibition, G2-phase arrest and apoptosis through a mechanism that at least partially targets RalA in K562 cells, suggesting that miR-181a might function as a tumor suppressor in hematopoietic cells." (PMID 22442671, 2012). "We also tested whether RalA or RalB could stimulate tumor growth in vivo." (PMID 21714887, 2011). "Evaluating the tumor-forming ability of WT-RALA expressing MCF7 and MiaPaCa2 cells showed a significant increase in tumor size, confirming the role of RALA in MCF7 and MiaPaCa2 tumorigenesis." (PMID 40568758, 2025). "Galectin-3 plays a key role in tumor progression and metastasis through c-MYC upregulation and YAP1/RalA/RalBP, conferring an aggressive phenotype." (PMID 40149589, 2025). "RALA and RALB adopt a plethora of roles in cancer, from supporting tumor growth to mediating invasion and metastasis." (PMID 39272901, 2024). "Furthermore, considering our observed changes in cytokine secretion following RALA and RALB loss in the MDA-MB-468 model, future experiments utilizing immunocompetent mice are needed to examine the role of the RALs in regulating the host anti-tumor immune response." (PMID 39272901, 2024). "RalA is a Ras effector, and its phosphorylation is also an important element of PP2A-mediated tumor suppression." (PMID 37048102, 2023). "RalA is required for Src-induced phospholipase D (PLD) and MMPs (MMP-2 and 9) activations, thereby promoting tumor formation and cell invasion ability." (PMID 36229838, 2022). "To address this issue, we focused on the members of the Ral family, RalA and RalB (collectively referred to as RalA/B), acting downstream of RAS and promoting metastasis of different tumor types in both mice and human." (PMID 33404012, 2021). "Finally, since both RALA and RHEB have been involved in Ras-mediated oncogenic transformation, direct inhibition of these proteins could be an alternative therapy, single or in combination, to treat tumours with oncogenic RAS mutations." (PMID 34359657, 2021). "For example, a specific inhibitor of RALA and RALB was effective in reducing both cell proliferation and tumour growth in lung cancer xenografts." (PMID 34359657, 2021). "Dephosphorylation of RalA leads to the subsequent inactivation of RalA, and of PP2A-Aβ losing its regulatory tumour suppressive capabilities, resulting in failure to reverse tumourigenic phenotypes and cellular dysfunction." (PMID 31623614, 2019). "Our observations that PPIP5K1 binds to the exocyst complex, RalA, and has anti-apoptotic properties suggest a possible link between PPIP5K and Ral GTPase-mediated tumor development." (PMID 31051014, 2016). "Their tumor sizes were marginally (not significantly) bigger than the RALA KO tumors and marginally (not significantly) smaller than the wild-type (WT)-RALA reconstituted tumors." (PMID 40568758, 2025). "How this localization can regulate tumor growth without affecting RALA activation is an open question." (PMID 40568758, 2025). "Together, these studies implicate S194 phosphorylation as vital for the role RALA has in tumor formation in MCF7 and MiaPaCa2 cells, independent of its activation and possibly regulated by its localization." (PMID 40568758, 2025). "Stable knockdown of either RALA or RALB decreased tumor growth in the TNBC MDA-MB-468 line but had no impact upon tumor growth in the HER2+ SKBR3 cell line." (PMID 39272901, 2024). "In contrast to the substantial negative effects on tumor growth observed when either RAL was silenced in the MDA-MB-468 cells, stable RALA and RALB silencing did not impact the in vitro or in vivo growth of the HER2+ cell line SKBR3." (PMID 39272901, 2024).
tumor (continued). "We also observed decreased CD31 staining indicative of reduced angiogenesis in MDA-MB-231 RALA-KO tumors (unpublished data), suggesting that this may be a universally important function of one or both RAL paralogs across tumor models." (PMID 39272901, 2024). "Interestingly, depletion of RALA increased the growth of 4T1 primary tumors, while depletion of RALB slowed primary tumor growth." (PMID 35626682, 2022). "RALA promoted the metastatic growth of TNBC cell lines, while RALB inhibited tumor metastasis." (PMID 36466919, 2022). "Neither RALA nor RALB were found to be required for primary tumor growth of PC3 cells but both paralogs contributed to bone metastasis." (PMID 35626682, 2022). "On the contrary, RalA expression did not change in tumor cells regardless of the in situ, invasive or metastatic localization." (PMID 30320548, 2018). "RalA protein expression was detected by IHC in 85.3% of tumor tissues from PCa patients, but without significant difference compared to BPH or normal control tissues." (PMID 27286458, 2016). "The localization of RALA and its regulation by RALA S194 phosphorylation could, in the absence of any effect on RALA activation, be responsible for regulating tumor growth." (PMID 40568758, 2025). "Thus, RALA S194 phosphorylation is needed for tumor formation, not affecting its activation, but possibly through its localization." (PMID 40568758, 2025). "Here, stable knockdown of either RALA or RALB did not impact the orthotopic tumor growth." (PMID 39272901, 2024). "In addition, the relationship between RALA level and various immune cell infiltration in tumor microenvironment (TME) has not been fully studied." (PMID 36466919, 2022). "When staining MDA-MB-468 tumors for the endothelial marker CD31, we found that RALB but not RALA loss decreased CD31 expression within both tumoral and stromal regions, suggesting that RALB may support angiogenesis in vivo and its silencing may impede tumor growth." (PMID 39272901, 2024). "RALA, but not RALB, was found to be significantly upregulated in HCC relative to non-tumor tissues." (PMID 35626682, 2022). "Importantly, inhibition of both RALA and RALB with the nonselective RAL inhibitor BQU57 significantly reduced tumor growth and metastasis in the TNBC cell line MDA-MB-231 and patient-derived xenograft models." (PMID 35626682, 2022). "RALA, but not RALB, was required for MDA-MB-231 tumor growth, invasion, and metastasis." (PMID 35626682, 2022).
cancer (54 papers, 2009 to 2025). A tumor composed of atypical neoplastic, often pleomorphic cells that invade other tissues. "The expression of RALA increases with cancer stage and high RALA is associated with worse overall survival." (PMID 35626682, 2022). "Somatic variants of RALA have been previously reported in cancers, and a total of 492 RALA somatic variants have been found in various tissues and organs, suggesting that pathogenic RALA somatic variants are associated with a wide range of disease phenotypes." (PMID 35846790, 2022). "RALA codes for Ras-related protein Ral-A, a protein implicated in several cancers, and pPSCA is a plasmid encoding prostate stem cell antigen." (PMID 33869008, 2021). "Taking into account that RalA is necessary for the anchorage-independent growth of cancer cells and its overexpression is associated with several different types of human tumors, our data are of particular interest." (PMID 34944949, 2021). "RalA and RalB share 82% amino acid identity and participate in numerous cellular processes such as endocytosis, exocytosis, actin reorganization and cell motility, proliferation and modulation of cancer-associated genes expression." (PMID 21714887, 2011). "Despite so, it remains uncertain how RalA signaling is activated in carcinomas apart from its canonical upstream RalGEF effectors." (PMID 36632230, 2023). "Depletion or knockout of RALGAP1 or RALGAP2 increases invasion and migration of cancer cells, with a concomitant increase in RALA or RALB activation." (PMID 35626682, 2022). "In this review we examine the functions of the RAL paralogs in normal cellular physiology and cancer biology with special consideration provided to situations where the roles of RALA and RALB are non-redundant." (PMID 35626682, 2022). "It is worth noting that RALA was shown downregulated in LUAD based on the TCGA bulk RNA-seq data, while almost all other cancer types showed an increase in RALA." (PMID 36483553, 2022). "Downregulation of several RALGEFs has been shown to decrease the invasion and migration of cancer cells both in vitro and in vivo through decreased RALA or RALB activity." (PMID 35626682, 2022). "RalA, a member of the Ras small GTPases superfamily, is critical for Ras-mediated human cancer cells proliferation." (PMID 36092663, 2022). "Almost all cancer types showed an increase in RALA, which was well-known as an endothelial activation marker." (PMID 36483553, 2022). "For those contributing to RAL-related cancer research, it is critical that studies rigorously address the contribution of both paralogs and account for potential confounding effects caused by the substantial similarities between RALA and RALB." (PMID 35626682, 2022). "Careful and thorough validation of antibodies and targeting RNAs is imperative if we are to unravel the independent functions of RALA or RALB across cancer." (PMID 35626682, 2022). "Together with evidence previously obtained in Caenorhabditis elegans, this demonstrates that the mechanisms by which RalA/B GTPases tune EV secretion levels are conserved throughout evolution and are notably at play in various cancer cell lines." (PMID 33404012, 2021). "RalA is also an important drug target due to its over activation in some cancers and these assignments will be extremely useful for NMR-based screening approaches." (PMID 31916136, 2020). "In vivo however, RalA and RalB appear to perform distinctive functions in normal cells and to play different roles in tumourigenesis and cancer progression." (PMID 31916136, 2020). "The two Ral GTPases, RalA and RalB, have crucial roles downstream Ras oncoproteins in human cancers; in particular, RalB is involved in invasion and metastasis." (PMID 30320548, 2018). "In doing so we have identified the role and regulation of a novel RalGEF in mediating the RalA activation in normal and cancer cells." (PMID 29460395, 2018).
cancer (continued). "Our team was interested in evaluating the level of RalA activation in CSC in comparison to differentiated cancer cells." (PMID 29047224, 2017). "Our data demonstrate a clear anti-cancer effect of RALA/iNOS gene therapy for metastatic breast cancer." (PMID 28325291, 2017). "We therefore examined the role of RalA and RalB in regulating Arf6 in K-Ras expressing pancreatic (MiaPaCa2) and H-Ras expressing bladder (T24) cancer cells." (PMID 27269287, 2016). "Ral GTPases are also activated in Ras-independent cancers through other mechanisms.Ral isoforms, RalA and RalB, though 82% identical regulate distinct cellular functions in normal and cancer cells." (PMID 27269287, 2016). "RalA and RalB have antagonistic effects on cancer cell migration, but possess overlapping functions in cell growth." (PMID 22442671, 2012). "One of them, RalA, is a v-ral simian leukemia viral oncogene homolog A (ras-related) involved in tumorigenesis and cancer invasion." (PMID 22442671, 2012). "It is important to examine whether the KRASG12X/+ cell lines’ cancer-related phenotypes depend on the RalA/B function and how Rgl2 and RalA/B status are altered in these cell lines." (PMID 38796063, 2024). "Furthermore, in certain cancers, Gal-3 enhances wnt/β-catenin signaling and activates Ras, Ras-Like Protein A (RalA) signaling, underscoring its comprehensive role." (PMID 37892182, 2023). "In addition, HCC cell populations enriched for the cancer stem cell marker CD133 were found to have significantly increased expression of both total RALA and active GTP-RALA." (PMID 35626682, 2022). "Whether and how RalA is involved in mTOR regulation of senescent-like cancer cell remains to be studied." (PMID 36267578, 2022). "By examining the differential expression of RagC, Rheb, RalA, Rab1A, Rab5, and Arf1 in cancer tissues (n = 369) and non-cancer controls (n = 160), we showed that RagC and Arf1 but not Rheb, RalA, Rab1A or Rab5 were significantly elevated in cancer tissues." (PMID 36267578, 2022). "Mutations in RAS family members and RAS signaling pathways are well-recognized causes of several dysmorphic syndromes and cancer, but germline mutations in RALA have not to our knowledge been previously associated with disease." (PMID 30500825, 2018). "Additionally, we have shown that the activation of RalA in cancer stem cells is higher in comparison with differentiated cancer cells." (PMID 29047224, 2017). "The results suggested by others 27 raise the possibility that AKA is phosphorylated by the Ca2+–calmodulin‐dependent pathway that may control the activation of RalA in cancer and normal cells." (PMID 29047224, 2017). "RalA mRNA expression was reported to be enhanced in advanced stages of cancer." (PMID 29047224, 2017). "The RalA staining in these cells was consistent with previous studies with other cancer cells." (PMID 27286458, 2016). "Among them, RalA is found to play important roles in tumorigenesis and cancer invasion." (PMID 22442671, 2012). "Together, we hypothesize that RILP interacts with RalGDS, and consequently inhibits its GEF activity, resulting in inhibition of RalA activation, thus suppresses the secretion and cytoskeleton reconstruction required for cell migration and invasion of cancer cells." (PMID 26469971, 2015). "Since IQGAP1 has been shown to associate with various small GTPases including cdc42 and Rac1, we examined whether or not RalA, previously shown to signal downstream of β-arrestin in cancer cells, can associate with IQGAP1." (PMID 23405264, 2013).